IL10 (interleukin 10)
Diseases named in the same sentence as IL10 in open-access papers (continued):
Sharing a sentence is not in itself a finding about the gene and the disease.
Obesity (continued). "Thus, in IBS with diarrhea, especially in its comorbid course with obesity, there is an imbalance of cytokines, which was manifested through a reduced content of IL-10 with increasing levels of TNFα and TGFβ1." (PMID 34621378, 2021). "We found positive correlation between all investigated cytokines except Il-10, which may confirm up-regulation of certain pro- and anti-inflammatory cytokines in obesity." (PMID 34444287, 2021). "This could be the case in our study since IL-10 levels are known to be increased in obesity conditions." (PMID 32244932, 2020). "IL-10 is decreased in subjects with impaired glucose tolerance and obesity." (PMID 32272872, 2020). "Interestingly, secretion of IL-18 and IL-10, cytokines reported to negatively regulate high fat diet-induced obesity and insulin resistance, and protect against hepatic steatosis, respectively, were increased in our HFHC-fed HIL mice." (PMID 33013934, 2020). "Interestingly, IL-10 in obese mice, displayed significant anti-obesity and anti-inflammatory effects, such as reduced serum total cholesterol, adipocyte size, proinflammatory cytokine secretion IL-6 in adipose tissue." (PMID 31261958, 2019). "Contrary to IL-10, elevated LP concentration may predict the development of obesity, myocardial ischemia, heart failure, and insulin resistance on the one hand." (PMID 31554241, 2019). "We found higher levels of IL-10 in AN patients compared to individuals with obesity and HCs." (PMID 31450770, 2019). "We observed increased gene expression of Gr1, Il6, and Il10 in the adipose of obese mice, suggesting an obesity-induced expansion in myeloid markers and cytokines that may promote the accumulation of immunosuppressive MDSCs." (PMID 31835454, 2019). "A similar effect was observed in TNF-α and interleukin-10, suggesting that genetic variants in adipokines do not have a significant effect in Mexican-Mestizo children obesity." (PMID 31354816, 2019). "The addition of RvD2 to placental trophoblasts led to increased IL-10 expression indicating that RvD2 acts as a cellular anti-inflammatory nutrient compound similar to its effect observed in hypothalamus against acute inflammation during obesity." (PMID 31500240, 2019). "Notably, immunoregulatory IL-10, TNF-α, and IL-1 have been linked to the pathophysiology of multiple chronic disorders including pain, obesity, diabetes, metabolic syndrome, and depression/anxiety, most of which are frequently observed clinically." (PMID 31554241, 2019). "Furthermore, elevated concentrations of IL-6, TNF-α, IL-10, and IFN-γ were associated with overweight and obesity (BMI above 25)." (PMID 31139232, 2019). "However, other cytokines, such as IL-1, monocyte chemoattractant protein 1 (MCP1), IL-10, and IL-17, are also altered upon obesity and have been extensively examined." (PMID 30591653, 2018). "Dysfunction of adipocytes, changes in metabolic profile or immune cells profile have been indicated in obesity, which may result in the alteration of IL-10 expression and chronic inflammation in AT." (PMID 29895283, 2018). "Altogether these results led to the hypothesis that IL10, acting individually or jointly with IL6, could prevent or ameliorate obesity as well as associated IR and lipid disturbances." (PMID 30158466, 2018). "In the present study, we showed that FGF21 promoted M2 macrophage polarization and M2-related anti-inflammatory cytokine such as IL10 in subcutaneous fat, which may act as a compensatory response to maintain glucose homeostasis in diet-induced obesity." (PMID 29348470, 2018). "HFD-induced obesity is accompanied by inflammatory status of IL-10 down-regulation in tissue." (PMID 29895283, 2018). "In contrast to TB, IL-10 may have a protective role in type 2 DM by reducing insulin resistance and obesity." (PMID 27057552, 2016).
Obesity (continued). "C-C motif chemokine receptor 2-knockout (Ccr2-KO) mice attributed insulin resistance in diet-induced obesity to the shift of from pro-inflammatory M1 macrophages into alternatively activated M2 macrophages and the reduction of anti-inflammatory cytokine interleukin-10 (IL-10)." (PMID 27703473, 2016). "Diet-induced obesity did not alter expression of Tnfa, Nos2, Il12, Il10, but was associated with a significant increase in Retnla expression and a small reduction in Il6, and Arg1 expression." (PMID 26956558, 2016). "We hypothesized that exercise training ameliorates HFD- induced cardiac dysfunction by mitigating obesity and inflammation through upregulation of IL-10 and downregulation of TNF-α." (PMID 25954207, 2015). "Consequently, increased levels of IL-10 could be associated with an exacerbated inflammatory profile in which the balance between pro- and anti-inflammatory cytokines contributes to chronic low-grade inflammation observed in obesity and T2D, as well as being involved in increased blood pressure." (PMID 26064986, 2015). "It is well established that obesity induced low grade inflammation is associated with elevated levels of pro-inflammatory cytokines such as TNF-α and reduced levels of anti-inflammatory cytokines such as IL-10." (PMID 26588700, 2015). "In future research, it might be promising to consider the role of anti-inflammatory cytokines such as IL-5, IL-10 and IL-13 in relation to physical activity in staying metabolically healthy despite the presence of obesity." (PMID 25781614, 2015). "In mouse models of obesity, macrophages switch from an anti-inflammatory M2 phenotype (producing IL-10) to a pro-inflammatory M1 phenotype, which overexpress inflammatory cytokines including IL-6 and TNF-α32 and are likely to be a major contributing source of these cytokines in adipose tissue." (PMID 25388403, 2015). "Furthermore, IL-10 improves insulin sensitivity and glucose transport, thereby having a protective role against obesity-induced insulin resistance." (PMID 25960614, 2015). "Based on the switch effects of IL-10 on macrophages, Th cells, IgG, IgA, and inhibition on proinflammation and Th1, IL-10 may have a great therapeutic potential in treating infections, inflammation, and related diseases including lung injury in obesity." (PMID 24899788, 2014). "Parameters of obesity, individual components of MetS, iron status and serum IL10 were evaluated." (PMID 23941335, 2013). "Other studies have challenged the protective effects of IL-10 in obesity-induced IR." (PMID 23675368, 2013). "Therefore further in vivo studies are required to evaluate the significance of IL-10 in obesity-induced IR." (PMID 23675368, 2013). "Previous studies have shown increased levels of IL-10 in diet-induced obesity in mice." (PMID 23843977, 2013). "Obesity impaired the ability of the spleen to synthesize cytokines, including IL-10." (PMID 23285260, 2012). "Furthermore, the number of T cells that secrete IL-10 dramatically decrease in proportion to increasing obesity." (PMID 23028874, 2012). "Our findings indicate that obesity reduces IL-10 production by the spleen and that spleen-derived IL-10 may protect against the development of NAFPD." (PMID 23285260, 2012). "Taken together, these observations suggest that spleen-derived IL-10 may prevent obesity-induced fat accumulation and chronic low-level inflammation in the pancreas." (PMID 23285260, 2012). "We therefore hypothesized that the obesity-induced reduction in IL-10 synthesis in the spleen may lead to inflammatory responses in the pancreas and to metabolic disorders." (PMID 23285260, 2012). "Based on the evidence in the literature, we hypothesize that obesity suppresses the synthesis of IL-10 and thereby results in chronic inflammation in the pancreas." (PMID 23285260, 2012).
Obesity (continued). "The adipokines with black lettering are those whose circulating levels are enhanced in obesity and whose total release by adipose tissue explants is enhanced in obesity: IL-6, IL-10, ACE, TGFβ1, ICAM-1, TNFα, IL-1β, PAI-1, and IL-8 that are released by nonfat cells." (PMID 20508843, 2010). "Background and Objectives: The pathogenesis of liver steatosis is associated with obesity and systemic inflammation, particularly in subjects with body mass index (BMI) above 40 kg/m2 and altered serum levels of tumor necrosis factor alpha (TNF-α) and interleukin-10 (IL-10)." (PMID 42195075, 2026). "We neither detected statistically significant differences in Il10 mRNA ratios nor in the expression of Treg activation markers between the groups, indicating that the immunosuppressive milieu in obesity can be reversed by weight loss." (PMID 40352719, 2025). "Furthermore, in healthy rats, we have shown that interactions between VN and the spleen can influence insulin secretion and IL-1β content in the endocrine pancreas, as well as alter IL-10 plasma levels and vagal activity, a response that is unknown in obesity." (PMID 40276696, 2025). "Additionally, the modulation of inflammatory cytokines, with decreased MCP-1 and increased IL-10 and GM-CSF, suggests that this functional yogurt could help counteract obesity-related inflammation." (PMID 39683663, 2024). "However, the results obtained in the analysis of the ratio between the pro-inflammatory cytokines and the anti-inflammatory cytokine IL-10 may support the suggestion that volunteers with obesity presents a systemic pro-inflammatory status." (PMID 39125408, 2024). "However, IL-10 acts as an anti-inflammatory factor in the immune response related to obesity." (PMID 36614227, 2023). "Therefore, increased IL-10 levels in the placebo group might represent feedback from elevated pro-inflammatory cytokines upregulated in obesity, including IFNγ." (PMID 36771387, 2023). "Therefore, our results proved that multiple IL10-MSCs transplantations could be used as an effective treatment for obesity and obesity-induced insulin resistance." (PMID 35715850, 2022). "This suggests that IL10 correlation with obesity might depend on gender." (PMID 35955698, 2022). "Notably, studies have revealed that the reduction in serum IL-10 levels in obese individuals probably results from the decreased production of IL-10 from the spleen, implying that spleen-derived IL-10 plays a vital role in the prevention of obesity-induced chronic inflammation." (PMID 35313972, 2022). "Results showed that IL10-MSCs could significantly counteract the HFD-induced obesity-related metabolic symptoms including body weight gain, hepatic and adipocyte lipids accumulation, glucose tolerance, insulin resistance, and serum lipid indicators, compared with unmodified MSCs." (PMID 35715850, 2022). "Moreover, in obese humans and rodents, adipocytes are significant sources of IL-10 in obesity." (PMID 35205336, 2022). "Therefore, we suggest that IL-10 regulation in obesity is specific to female scWAT." (PMID 36313784, 2022). "Previous studies suggest that IL-10 may have a specific role in obesity/T2D." (PMID 36313784, 2022). "Therefore, IL10 plays an important role in controlling inflammation and modulating immune responses, which can well contradict the inflammation in adipose tissue and insulin resistance in obesity." (PMID 35715850, 2022). "Therefore, IL10-MSCs were injected every 2 weeks to treat HFD-induced obesity." (PMID 35715850, 2022). "Therefore, this evidence may support the regulative role of TNF-α on IL-6 and IL-10 concentration levels in adults with overweight or obesity who experimented an alteration of monocyte metabolism after exercise training." (PMID 34948868, 2021). "However, in other settings, such as ankylosing spondylitis and obesity, defective IL-10-mediated downregulation of CD8+ T cell responses by B cells may promote unwanted inflammation and tissue damage." (PMID 33995344, 2021).
Obesity (continued). "Thus it would be important to determine whether increased IL-10 levels in aging, may play a beneficial role in the context of obesity-driven metabolic disease by ameliorating disease severity." (PMID 35822048, 2021). "Similarly, in the presence of the three clinical comorbidities (obesity, diabetes, and oxygen saturation ≤ 93% or >50% lung involvement on CT), the probability of progression is 1% with lower IL-10 and IL-12 (p70) levels, but 97.5% with elevated levels of these biomarkers." (PMID 34386533, 2021). "Interestingly, Biocarta also found significant overrepresentation in two well-known anti-inflammatory pathways: the PPARγ-related obesity pathway (Systemic name M22017) and the IL-10/JAK/STAT signaling pathway that result in the repression of TNFα, IL-1, and IL-6 (Systemic name M6778)." (PMID 33256749, 2020). "Thus, IL-33 had a protective effect against obesity, insulin resistance and diabetes in animal models due to the reduction of resistin expression, accumulation of Th2 cells and IL-5, IL-13 and the suppression of T effectors cells by IL-10 releasing." (PMID 32824505, 2020). "The expression and secretion of MCP-1, IL-6, and resistin are increased in obesity, playing an important role in the appearance of the inflammatory M1 type macrophages, and decreasing the expression and production of the protective adiponectin and IL-10 in the adipose tissue." (PMID 31438590, 2019). "We postulate that females, due to the need to handle larger weight changes during pregnancy and lactation, exhibit higher levels of protective anti-inflammatory IL-10 and that increased levels of anti-inflammatory cytokines in female may afford them protection from obesity-induced inflammation." (PMID 30254630, 2018). "However, in obesity, the decline in adipose tissue eosinophils in mice might promote a pro-inflammatory macrophage predominance due to less eosinophil-derived IL-4 and IL-10." (PMID 29479350, 2018). "Therefore, we suspect that if these used GAGs could be conjugated with IL-10 in serum, as is our hope, then GAG-IL-10 could be causing the anti-obesity effect." (PMID 28327528, 2017). "However, obesity frequently concurs with both obstructive sleep apnea and obesity, which has made it difficult to determine whether IL-10 could be specifically altered during OSA and thus contribute to metabolic disease regardless of obesity." (PMID 25944984, 2015). "When normal-weight boys were separately assessed from ow/obesity boys, the association between testosterone and serum ferritin became stronger (β = -0.9628, p<0.0001), but the association between testosterone and IL-10 became non-significant (β = 0.1140, p = 0.4065) after adjusting for covariates." (PMID 26646112, 2015). "In our study, we did not observe an association between sera IL-10 levels and obesity." (PMID 24741576, 2014). "Interleukin-10 may play a protective role in obesity-induced metabolic dysregulation and IR." (PMID 23675368, 2013). "Indeed, low IL-10 production has been demonstrated in obesity." (PMID 23285260, 2012). "However IL-10 may be an anti-inflammatory adipokine primarily released by the nonfat cells, whose circulating levels as well as in vitro release are elevated in obesity." (PMID 20508843, 2010). "Obesity is associated with a chronic low-grade inflammation, and inflammatory markers related to obesity include TNF-α, IL-6 [24,26,27,], and the anti-inflammatory cytokine IL-10." (PMID 40125475, 2025). "In our cohort, individuals with obesity showed elevated plasma Ang II, heightened concentrations of IL-1β, IL-6, and TNF, and reduced IL-10, supporting the presence of a dysregulated inflammatory state exacerbated by viral infection." (PMID 41562075, 2025). "Circulating MAITs in obesity and metabolic disease are characterized by increased IL2, granzyme B, IL17, IFNγ, and TNFα, and less IL10 compared to healthy controls." (PMID 38674935, 2024).
Obesity (continued). "Regarding the correlation analyses of RAS components with hepatic cytokines in individuals with obesity and MASLD, a significant positive correlation was observed between ACE, and all analyzed cytokines (TNF-α, IL-6, IL-4, IL-13, IL-10)." (PMID 39337863, 2024). "Among the most well-studied cytokines concerning obesity are the inflammatory cytokines such as TNF-α (tumor necrosis factor alpha), interleukin-6 (IL-6), and the anti-inflammatory cytokine IL-10." (PMID 39180618, 2024). "There is an increase in the levels of both pro-inflammatory and anti-inflammatory cytokines in OSA patients with obesity (IF-γ and IL-1RA, respectively) or hypertension (CCL3 and IL-10, respectively)." (PMID 36769452, 2023). "In a recent study, a link between obesity and ovulatory failure in PCOS patients was explored in mice, and increased IL-10 levels were found to weaken folliculogenesis." (PMID 36677054, 2023). "Therefore, we suggest that, besides TNF-α, there should be other factors in the group with obesity involved in insulin resistance, like high levels of leptin, along with low levels of adiponectin and IL-10, which may interfere with inflammation control and insulin sensitivity." (PMID 37215211, 2023). "Nonetheless, the adipose protein profile indicates sex- and RELMα-dependent effects of diet-induced obesity, which correlates with increased proinflammatory CCL2, and decreased anti-inflammatory and Th2 cytokines, IL-10, GM-CSF, and IL-5, respectively." (PMID 37162190, 2023). "IL-10 secreted from regulatory T (Treg) cells suppresses white adipose tissue (WAT) browning and induces obesity." (PMID 37334370, 2023). "Obesity and HFD augmented the expression of the TNF-α pro-inflammatory gene and reduced the expression of anti-inflammatory (IL-10) genes." (PMID 38116571, 2023). "Inflammatory biomarkers including hs‐CRP, IL‐6, IL‐4, IL‐1B, IL‐10, and TNF‐α have also been shown to be connected with obesity, diabetes, and CVD." (PMID 36911829, 2023). "In this study, we established overexpressing IL10 HUCMSCs (IL10-MSCs) and intravenously injected into mice with HFD feeding to investigate their effects on obesity and metabolic disorders." (PMID 35715850, 2022). "Furthermore, high levels of IL‐10, an anti‐inflammatory cytokine, appear to be a hallmark of hyperinflammation during severe SARS‐CoV‐2 infection, and some studies included in this review observed that IL‐10 levels predict poor outcomes in COVID‐19 patients with obesity." (PMID 35837843, 2022). "IL-10 secreted from Treg cells, including VAT Treg cells, can drive insulin resistance in obesity by suppressing adipocyte energy expenditure and thermogenesis." (PMID 35359918, 2022). "The aim of this study was to compare the impact of obesity and T2D on WAT IL-10 levels in men versus women." (PMID 36313784, 2022). "Consistent with the heightened activation of PRRs, ELISA showed that serum cytokine concentrations of TNF-α, IFN-γ, IL-1β, IL-6, and IL-17A were significantly induced with obesity, as was anti-inflammatory TGF-β and IL-10." (PMID 36406423, 2022). "Certain inflammatory enzymes like interleukin-2 (IL-2), interleukin-10 (IL-10), interferon-γ (IFN-γ), and interleukin 1-α (IL1-α) were found to differ between participants with obesity and with normal BMI." (PMID 36612361, 2022). "Furthermore, IL10 shares a similar structure and function with leptin, and over-expression of murine IL10 in skeletal muscle by adeno-associated virus (AAV) transfer meliorated hyperphagia, obesity, glucose intolerance, and insulin resistance in leptin deficiency mice by substituting for leptin." (PMID 35715850, 2022). "Other nominally significant associations were established between WHOCS scales and: IFNL4 rs12979860, ACEIs, obesity, ARA-II, HCP5 rs2395029, ACE rs1799752, DPP4 rs17574, HMOX1 rs2071746, IL10 rs1800896, IL6 rs1818879, NFKB1 rs28362491, and MX1 rs469390." (PMID 35636966, 2022).